MMP9 (matrix metallopeptidase 9)
Diseases named in the same sentence as MMP9 in open-access papers (continued):
Sharing a sentence is not in itself a finding about the gene and the disease.
tumor (continued). "In vitro and in vivo, we proved that PDGF-D significantly promoted tumor growth and invasion through up-regulating MMP2 and MMP9, and inducing EMT." (PMID 24646915, 2014). "Equally, the tumor suppressor, PDCD4 is directly targeted by miR-21 in HCC and as a result, the downstream molecular signalling cascade including MMP-2, MMP-9 and phospho c-jun were all shown to be affected." (PMID 24670365, 2014). "Indeed, the role that α3β1 plays in promoting COX2 gene expression extends to other genes with pro-tumorigenic/pro-metastatic roles, including MMP-9, suggesting that blocking the gene regulatory functions of this integrin might suppress multiple tumor cell functions that drive carcinogenesis." (PMID 24950714, 2014). "When triggered by SEMA7A, macrophages elevate secretion of angiogenic CXCL2/MIP-2 while silencing SEMA7A resulted in decreased tumor angiogenesis, and lower levels of CXCL2/MIP-2, CXCL1 and MMP-9." (PMID 25071604, 2014). "Real-time PCR analyses were carried out to detect the expression of VEGF, MMP9 and TGF-β in tumor tissues." (PMID 24824968, 2014). "However, the functional implications for progression and metastasis of tumor cell-produced MMP9 have remained obscure, as previous experimental studies measuring metastasis as an endpoint have employed transgenic models best suited for probing the role of stromal cell-produced MMP9." (PMID 24811362, 2014). "It is generated through proteolytic cleavage of circulating plasminogen by a series of enzymes from the tumor environment, including the MMPssuch as MMP-2, MMP-7, MMP-9, and MMP-12." (PMID 25549350, 2014). "MMP9 and MMP14, which have been regarded as regulators of tumor migration and invasion, are known to be involved in cell migration and invasion and frequently found to be upregulated in HNSCC." (PMID 25268950, 2014). "Our previous study demonstrated that CD147 in tumor cells modulates fibroblasts, as well as HCC cells themselves to produce MMP-2 and MMP-9, promoting HCC invasion and metastasis." (PMID 24996644, 2014). "Expression of oncoproteins related to tumor metastasis, such as MMP2, MMP9, and CD44, was also significantly reduced." (PMID 24387290, 2014). "As MMP-2 and MMP-9 have a critical function in tumor cell invasion, the inhibitory effect of icotinib on the expression of MMP-2 and MMP-9 was investigated." (PMID 25120710, 2014). "Although various MMPs have been implicated in acquisition of invasive and metastatic properties by tumor cells, MMP-2 and MMP-9, which degrade type IV collagen, a major component of basement membranes, are majorly associated with metastasis." (PMID 25296976, 2014). "It has been proposed that STC2 facilitates tumor cell migration through epithelial-mesenchymal transition (EMT) and upregulation of MMP-2 and MMP-9 in hypoxic conditions." (PMID 24606961, 2014). "Microglia (MG) make up almost one third of the non-tumor cells found in GBM tissue sections and are responsible for secreting MMP-9, EGF, and VEGF." (PMID 24518612, 2014). "Since its original identification as a leukocyte gelatinase/type V collagenase and tumour type IV collagenase, gelatinase B/matrix metalloproteinase (MMP)-9 is now recognised as playing a central role in many aspects of tumour progression." (PMID 24473089, 2014). "The tumor suppressor RECK is able to suppress tumor angiogenesis, invasion and metastasis, inhibiting MMP-2 and MMP-9." (PMID 25909813, 2014). "Our data showed that, while MMP9 and MMP15 (MT2-MMP) expression in tumor cells was negligible in both Apcmin/+ and Apcmin/+/Stat3IEC-KO mice, MMP7 expression in tumor cells was significantly lower in Apcmin/+/Stat3IEC-KO mice." (PMID 24995503, 2014). "The 5 randomly selected gene expression changes observed using the Human Tumor Metastasis RT2 Profiler PCR array (CXCR4, CXCL12, MMP2, MMP9 and MMP13) were confirmed using qPCR." (PMID 24179538, 2013).
tumor (continued). "The inhibitory effect of artesunate on the tumor of the mouse model as well as ICAM-1 and MMP-9 protein expressions were determined by Western blot." (PMID 24229621, 2013). "We demonstrated that an MMP-9 mAb inhibited the transendothelial migration of both tumor lines and propose that MMP-containing blebs from tumor cells augment local MMP levels." (PMID 24194929, 2013). "MMP-2 and MMP-9 are critical enzymes for ECM degradation, which is a critical step in tumor metastasis." (PMID 23877152, 2013). "Cyclin E1 and MMP9 expression levels were reduced, indicating that these two downstream genes are regulated by NR5A2 and are suggested to participate in neoplasm proliferation and invasive process induced by miR-139-5p, respectively." (PMID 24204738, 2013). "To further explore the mechanism of EFEMP1 on tumor invasion and migration, we assayed culture supernatants from HEC-1B, RL95-2 and transfected cells for the concentration of MMP-2 and MMP-9." (PMID 23840707, 2013). "Previous studies have shown that MMP-9 is up-regulated during docetaxel treatment and that inhibition of MMP-9 enhances it anti-tumor effect." (PMID 24155892, 2013). "The top of the MMPs list was MMP-9 (40-fold higher in NPC tumors compared with control), one of the best-studied proteinases involved in promoting tumor invasion and metastasis." (PMID 24243817, 2013). "Inhibition of IL-17A at tumor sites significantly suppressed CD31, MMP9, and VEGF expression in tumor tissue." (PMID 23372655, 2013). "Of these overexpressed genes, 5 (CXCR4, CXCL12, MMP2, MMP9 and MMP13) were selected on the basis of their strong correlation with tumor metastasis and were validated by qPCR." (PMID 24179538, 2013). "Silencing MMP-9 and/or uPAR decreased cell adhesion to ECM proteins—a process known to promote tumor cell migration and invasion." (PMID 24325546, 2013). "MMP2 and MMP9 are activated by CREB and appear to play important roles in tumor invasion and metastasis." (PMID 24113161, 2013). "majorana significantly reduced the expression of several NFκB downstream target genes (MMP-2, MMP-9, uPAR, ICAM-1 and VEGF) involved in tumor metastasis." (PMID 23874773, 2013). "We first show that tumor cell interactions with macrophages resulted in increased expression of EMMPRIN and induction of MMP-9 and VEGF." (PMID 23874303, 2013). "Specifically, we show that EVs are potent stimulators of MMP-9, IL-6, TGF-β1 and induce the secretion of extracellular EMMPRIN, which all play a role in driving immune evasion, invasion and inflammation in the tumor microenvironment." (PMID 23936495, 2013). "High levels of MMPs, particularly MMP-9, release and activate VEGF that is trapped by the ECM, and allow migration of endothelial cells, as well as leukocytes and metastatic tumor cells." (PMID 23785333, 2013). "It has been reported that MMP-9 cleaves ICAM-1 and participates in tumor cell resistance to natural killer cell-mediated cytotoxicity." (PMID 23803661, 2013). "In particular, colon metastases are known to induce MMP2 and MMP9 expression in stromal cells, and MMP inhibitors reduce tumor growth and metastasis in animal models." (PMID 24023955, 2013). "Among which, tumor invasion factors namely matrix metalloprotease-2 (MMP-2) and MMP-9 were partly responsible for the astrocyte media-induced tumor cell invasion." (PMID 24324647, 2013). "However, previously we were able to show that treatment with GM-CSF neutralizing antibodies almost abrogated tumor invasion in OTCs of a highly GM-CSF expressing HNSCC cell line (HNO97) 16 and can now demonstrate that this is associated with a decreased secretion of MMP-9." (PMID 23634280, 2013). "MMP2 and MMP9 are important mediators for tumor progression and metastasis, and in our experiments we observed the levels of pro- and active-MMP2, MMP9 were the lowest in the combination therapy group among three groups." (PMID 24304581, 2013).
tumor (continued). "Regarding angiogenesis, here we demonstrate that the same autoAbs that increased MMP-9 activity in MCF-7 cell supernatants can trigger VEGF-A expression and tumor-induced angiogenesis." (PMID 23460876, 2013). "In univariate analysis, tumour characteristics such as size, mode of growth, regional lymph node metastases, tumour cell MIB-1 LI and MMP-9 and uPA expressions in tumour-adjacent fibroblasts, were associated with both survival and disease-free intervals." (PMID 23289974, 2013). "The expression of MMP-9 and VEGF is regulated by NF-κB and has been reported to play an important role in tumor invasion." (PMID 23618129, 2013). "In conclusion, we show that co-cultures of tumor cells and macrophages induce EMMPIN expression, as well as production of MMP-9 and VEGF, mostly by the macrophages." (PMID 23874303, 2013). "The gelatinases, MMP-2 (gelatinase A) and MMP-9 (gelatinase B), are two members of the MMP family and play a critical role in tumor invasion and metastasis." (PMID 23935727, 2013). "This stimulatory activity of EVs to induce secretion of TGF-β1, MMP-9, IL-6 and EMMPRIN, suggests a role of the EVs in driving tumor progression by stimulating factors important for immune evasion, invasion and inflammation." (PMID 23936495, 2013). "The results showed that MDSCs from IL-17−/− tumor-bearing mice expressed lower levels of Arg-1, MMP9, and S100A8 than those from wild-type tumor-bearing mice." (PMID 24453427, 2013). "In these niches, granulocytes secrete prokinectin 2 to attract tumor cells and MMP-9 and induce neighbor cells to secrete VEGF to facilitate the arrival of tumor cells." (PMID 23577028, 2013). "When mice bearing nasopharyngeal carcinoma tumors were treated with endostar (recombinant endostatin), the treatment led to a significant decrease in MMP-9 and VEGF expression levels and normalized the tumor vasculature." (PMID 23365550, 2013). "Tumor sections were stained with antibodies to both α-SMA, a marker for stromal myofibroblasts, and MMP-9." (PMID 23407024, 2013). "In Dittmer study reported that over-expression of ETS1 would promote tumor invasion due to its ability to activate the MMP1, MMP3, MMP9 and uPA as well as of VEGF in tumorigenesis." (PMID 23405089, 2013). "Owing to above results we concluded that tumor cells obtained migratory and invasive ability indicated by MMP2 and MMP9 stimulation, whereas ZEB1 required further elucidation in other ccRCC cell lines." (PMID 24023875, 2013). "Matrix metalloproteinase-9 (MMP-9), by degrading components of the extracellular matrix and thus promoting the release of growth factors, is important in tumor growth and tumorigenicity." (PMID 23760084, 2013). "CD204(+) macrophages reportedly exhibit a tumor-promoting function in several tumors by secreting matrix metalloproteinase (MMP)-1, MMP-3, MMP-7, MMP-9, MMP-12, vascular endothelial growth factor (VEGF), and transforming growth factor (TGF)-β." (PMID 24376714, 2013). "Immunohistochemical staining for MMP9 and MDM2 was performed using archived tumor blocks from 321 women who underwent surgical resection for IDC at the First Affiliated Hospital of Nanjing Medical University, China between January 2002 and December 2003." (PMID 24236052, 2013). "Given that MMP2, MMP9, vimentin, and ZEB1 were regarded as potential elemental genes implying the pro-metastatic state and higher malignancy of tumor cells, as well as E2F1 downstream target genes, RT-PCR was performed to detect changes in mRNA levels." (PMID 24023875, 2013). "IHC analysis confirmed markedly increased CCL2, pSTAT3, EMT markers (MMP9 and Snail) and F4/80-positive macrophages in TRAMP-C1 siAR tumours, and the treatment with CCR2atg significantly reduced these up-regulated markers." (PMID 23982944, 2013). "The final anti-tumor effects were measured by the tumor volume and weight as well as the intratumoral activity of MMP2 and MMP9." (PMID 24304581, 2013).
tumor (continued). "Rat neurological signs, survival time, tumor size, hematoxylin and eosin (HE) staining and immunohistochemical staining for MMP-2, MMP-9 and β-catenin were compared." (PMID 23946812, 2013). "A mouse xenograft tumor model that overexpressed beta-arrestin, a known regulator of MDM2, showed increased MMP9 activity with more aggressive tumors." (PMID 24236052, 2013). "SNAI2 has a positive effect on α3β1-mediated invasiveness of tumor cells, since SNAI2 promotes the production of MMP-2 and MMP-9." (PMID 24260309, 2013). "The cytokine TNF-α promotes tumor proliferation by inducing the release of matrix metalloproteinase (MMP), particularly the gelatinases MMP-2 and MMP-9, which promote tumor growth and metastasis." (PMID 23977085, 2013). "MMP-9 and ICAM-1 have been shown to be expressed in response to NF-κB activation, and are known to be major mediators of tumor cell invasion." (PMID 22768286, 2012). "Early attempts to identify MMPs responsible for mediating tumor invasion focused on soluble MMPs (particularly MMP-2 and MMP-9), and expression of these MMPs correlated with the neoplastic phenotype." (PMID 24213464, 2012). "Using a rodent model, we previously identified that MMPs were highly expressed in the tumor-bone microenvironment with subsequent studies revealing that MMPs such as MMP-7 and MMP-9 were largely localized to osteoclasts in this setting." (PMID 22238668, 2012). "MMP-9 mRNA was expressed in cancer epithelial cells and stromal cells, while MMP-2 mRNA was predominantly expressed in tumor stromal cells." (PMID 22159401, 2012). "In EW, the proinflammatory microenvironment (interferon, IFN) is more often seen in metastasis than in primary tumours and participates in neoangiogenesis (VEGFR secretion) and the metastatic potential (MMP9 secretion)." (PMID 23226965, 2012). "MMP-9 correlated with WHO grade (p < 0.001); it was more often positive in high to moderately differentiated tumours." (PMID 23216739, 2012). "Mechanistic studies indicate that ATX promotes tumor cell invasion via LPA, their receptors and via MMP-9." (PMID 22952646, 2012). "Gelatinases (MMP2 and MMP9), two important isoforms in the MMP family, are considered to be closely correlated with tumor invasion and metastasis." (PMID 23226772, 2012). "Normally, MMP-9 is expressed at a low level in many cell types and while tight control of MMP-9 activity is essential for normal development, abnormal expression of MMP-9 contributes to disease processes such as tumor growth and metastasis." (PMID 22879913, 2012). "Among MMPs, MMP-2 (gelatinase-A) and MMP-9 (gelatinase-B) are particularly upregulated in SACC and contribute to the invasion of tumor cells by degrading the ECM." (PMID 22200897, 2012). "Activities of proMMP-9 (the latent form of MMP-9) and active MMP-9 in the tumor were higher in patients with recurrence." (PMID 22200690, 2012). "Overall survival was significantly shorter in patients with high tumour and stromal MMP-2 and MMP-9 expression, and tended to be shorter in patients with low ColIV expression." (PMID 23107277, 2012). "To understand the mechanism of apigenin in inhibiting metastasis, we found that apigenin greatly inhibited MMP-9 expression and p-AKT and p-p70S6K1 levels in the tumor tissues compared to the control group." (PMID 22837693, 2012). "Solid evidence implicates MMPs in tumor invasion and metastasis, and the link between TGF-β and MMP-9 has been extensively studied." (PMID 22614218, 2012). "The initial step of tumor cell invasion is characterized by BM breakdown, a process dependent on type IV collagen-degrading enzymes, mainly MMP2 and MMP9." (PMID 23031673, 2012). "Therefore, SCE-H may help inhibit tumor invasion or progression via MMP-9 and/or ICAM-1." (PMID 23024755, 2012).
tumor (continued). "One study assessed the change in salivary MMP-9 protein levels 2 hours after 5-minute BQ chewing stimulation (BQCS) in non-BQ users and the expression profile of this proteinase in saliva and tumor specimens of OSCC patients with a history of BQ use." (PMID 22912735, 2012). "These cells expressed MMP-9, which released matrix-bound VEGF and by that increased tumor angiogenesis." (PMID 24213237, 2012). "Hagemann and colleagues demonstrated that coculturing TAMs with tumor cells can promote the expression of MMPs, especially MMP2 and MMP9, in TNF-α-dependent manner." (PMID 22778768, 2012). "Proteins including matrix metalloproteinase-9 (MMP9), cathepsin B, matrilysin, and laminin have been identified as being highly expressed in tumor budding." (PMID 22919486, 2012). "Since MMPs play critical roles in tumor cells invasion, we examined the effect of blocking EMMPRIN by its antibody on the enzyme activity of MMP-2 and MMP-9 using gelatin zymography." (PMID 22200897, 2012). "The mechanisms by which the decreased expression of MMP9 and MMP10 and the increased of TIMP4 are responsible for the depressed growth and invasion of tumor cells due to S100A4 silencing, are currently being investigated in our laboratory." (PMID 22200787, 2012). "MMP-2, MMP-9, and MMP-14 have been reported to be involved in tumor angiogenesis and extracellular matrix remodeling." (PMID 22496834, 2012). "The membrane-associated MMP inhibitor, RECK (reversion-inducing cysteine-rich protein with Kazal motifs), is able to suppress tumor invasion and metastasis by negatively regulating MMP-2, MMP-9 and MMP-14." (PMID 22260435, 2012). "Considering activation of MMPs, MT1-MMP is a key enzyme in tumor angiogenesis and metastasis: it hydrolyzes a variety of ECM components, and is a physiological activator of pro-MMP-2 and MMP-9." (PMID 22695075, 2012). "The arrival of circulating metastatic tumour cells in the lungs depends on chemokines and adhesion, then extravasation into target tissues depends on proteinases (MMP2, MMP9)." (PMID 23226965, 2012). "In exploring ColIV expression, we also found that tumour expressions of MMP-2 and MMP-9 showed certain variations." (PMID 23107277, 2012). "The expression of ICAM-1, MMP-9 and VEGF, which are involved in tumor cells invasion and metastasis, is known to be regulated by NF-κB." (PMID 22768286, 2012). "A recent report indicated that oesophageal tumors from obese patients express more MMP9 and that co-culture of VIS adipose tissue explants with tumor cells up-regulated MMP2 and MMP9." (PMID 22469146, 2012). "Inhibition of miR-21 leads to increasing levels of RECK, a membrane-anchored glycoprotein that inhibits tumor cell invasion by regulating MMP-2, MMP-9 and MT1-MMP." (PMID 22642976, 2012). "In this study, by using MMPI to inhibit MMP-9 activity, the role of MMP-9 in the process of embryos invading tumor cells in vitro was explored." (PMID 22672566, 2012). "IL-4 stimulation of macrophage-containing cultures resulted in enhanced tumor cell invasion evidenced by degradation of the basement membrane, enhanced collagenolytic activity and increased MMP-2 and MMP-9." (PMID 22792213, 2012). "TAMs appear to influence the microenvironment to facilitate migration of tumor cells by the release of MMPs, for example, MMP-2, MMP-7, and MMP-9." (PMID 23316105, 2012). "64Cu-DOTA-CTT was found to inhibit MMP-2 (EC50 = 8.7 μM) and MMP-9 (EC50 = 18.2 μM) with similar affinity as CTT (EC50 = 13.2 and 11.0 μM, respectively), but in vivo was a poor tumor imaging agent due to its low affinity and instability." (PMID 23201642, 2012). "When pro-tumor growth mediators such as IL-6, IL-10, MMP-9, and VEGF are the primary secreted factors from TAMs, then tumor angiogenesis, enhanced cell motility, and increased tumor cell invasion are facilitated." (PMID 21385454, 2011).